LINC00639 (long independently transcribed non-coding RNA 639)
Gene: Long non-coding RNA gene on chromosome 14 (38,699,825 to 38,948,289, reverse strand). Ensembl gene ENSG00000259070.
Diseases named in the same sentence as LINC00639 in open-access papers:
LINC00639 is named in the same sentence as 3 diseases in open-access papers, as found by Europe PMC text mining. Sharing a sentence is not in itself a finding about the gene and the disease. The quoted sentences say what the papers report.
Cognitive impairment (1 paper, 2022). Abnormal cognition is characterized by deficits in thinking, reasoning, or remembering. "A recent study reported that LINC00639, the target gene of miR-1227, was downregulated in HIV-associated dementia (HAD), a kind of cognitive impairment induced by HIV infection." (PMID 35528544, 2022).
tumor (1 paper, 2022). "Surprisingly, RP4-676L2.1 and LINC00639 were also not successfully validated to be consistent difference of expression between tumor and normal lung tissue by qPCR." (PMID 35183135, 2022).
LINC00639 also shares sentences with these, for which no sentence is quoted: HIV-associated dementia (1 paper).